BCL2 (BCL2 apoptosis regulator)
Diseases named in the same sentence as BCL2 in open-access papers (continued):
Sharing a sentence is not in itself a finding about the gene and the disease.
tumor (continued). "Furthermore, inhibition of the VILIP3/NFκB/Bcl-2 regulatory axis was also observed in the desloratadine-treated Huh7 and HepG2 tumor xenografts." (PMID 36617552, 2023). "Additionally, studies have indicated a significantly higher prevalence of Bcl-2-positive tumor cells in SCC compared to asymptomatic AK." (PMID 38068343, 2023). "In vivo SERS signals at the tumor site were lower than those of the surrounding tissue after one day of injection of the NPs, suggesting that cancer cells exhibited higher BCL2 expression in vivo after the injection of Au@GO NP‐Cy5‐BCL2‐NACs." (PMID 36683237, 2023). "Tumor cells could fine-tune the balance between energy requirements and ROS status, and Bcl-2 and COX regulate mitochondrial respiration and the intracellular ROS environment." (PMID 37954849, 2023). "The nano-complexes showed more than three-fold and two-fold decreases in tumor volume and weight, respectively, compared to control and free siRNA, indicating successful targeted delivery of siRNA to the cancer site and suppression of BCL2." (PMID 37111795, 2023). "Finally, anti-apoptotic marker, Bcl-2 was higher in ALDH+ population of Tumor but decreased in ALDH+ of T+25." (PMID 38144525, 2023). "Currently, the main mechanisms of Aconitine anti-tumor properties have been reported in the literature, with a primary focus on the expression of Bax, Bcl-2, Caspase-3, and other proteins, reactive oxygen species damage and the triggering of apoptosis and autophagy in tumor cells." (PMID 37180714, 2023). "Altogether, these outcomes demonstrate that CTSG may act as a tumor suppressor gene via Akt/mTOR/Bcl2-mediated anti-apoptotic signaling inactivation, and CTSG represents a potential therapeutic target in CRC." (PMID 37151875, 2023). "Furthermore, the Bax/ Bcl-2 ratio indicates the sensitivity of cells to apoptosis was lower in the DMH + IR group thus favoring tumor growth." (PMID 37493814, 2023). "Furthermore, tumor cells promote survival by increasing Bcl-2 anti-apoptotic proteins and decreasing apoptotic proteins such as Bax." (PMID 36624422, 2023). "In addition, the tumor suppressor inhibits the anti-apoptotic factor Bcl-2 in response to DNA damage." (PMID 37505740, 2023). "This strong BCL2 expression may be one of the reasons for the strong anti-tumor effect of venetoclax-containing conditioning regimens." (PMID 36629738, 2023). "However, Snaillo tumours showed reduced cleaved caspase-3 staining, a marker for apoptosis, and significantly increased expression of the anti-apoptotic protein Bcl-2." (PMID 36788501, 2023). "The percentage of BCL2(+) tumor cells was variable, between 20% and maximum 90%." (PMID 38024830, 2023). "After absorption of PC in tumors and irradiation with laser, ROS are produced in tumor cells to induce extracellular apoptosis by increasing the activity of Caspase-8 and Caspase-3 and decreasing the activity of Bcl-2, an important factor for cell proliferation." (PMID 37994159, 2023). "In all patients, we evaluated BCL-2 expression on tumor tissue." (PMID 37935707, 2023). "Subsequently, a decrease in Bcl-2 expression makes the tumor less attractive to the immune system." (PMID 37185731, 2023). "Mechanistically, it may regulate the expression levels of Bax and Bcl-2 through the NF-κB signaling pathway, ultimately inhibiting tumor cell proliferation through autophagy." (PMID 37180714, 2023).
tumor (continued). "Tumor cells achieve a balance between fine-tuned energy requirements and mitochondrial ROS status through the regulation of mitochondrial respiration to maintain an optimal survival environment, with key players including Bcl-2 and cytochrome c oxidase (COX)." (PMID 37954849, 2023). "A. membranaceus polysaccharides can inhibit Bcl-2 expression to induce tumor cell apoptosis." (PMID 36951135, 2023). "In addition, the tumor infiltrating TCR-JUN T cells showed higher expression of anti-apoptotic Bcl-2, indicating that TCR-JUN T cells are less apoptotic than TCR T cells." (PMID 37215108, 2023). "Overexpression of Bcl‐2 has been detected in a variety of malignant tumor cells." (PMID 36916294, 2023). "Our results show that of bcl-2 over expression may represent tumor de-differentiation and more aggressive behaviour of NSCL tumors." (PMID 36766867, 2023). "However, the Bax/Bcl-2 expression level was maintained constant in the primary tumor and CT26 cells." (PMID 37864254, 2023). "The upregulation of TNF-α, IL1β, and Bcl-2 genes suggests that the CLT was able to initiate an inflammatory response to combat the tumor, while the downregulation of the Bax and Beclin1 genes indicates that the CLT was able to reduce the risk of apoptosis in the liver." (PMID 37160480, 2023). "BAX and BCL-2 play important roles in regulating tumor growth." (PMID 36913356, 2023). "MCL-1 is upregulated in senescent tumor cells and in cells that express low levels of BCL-2." (PMID 37601693, 2023). "Moreover, 12.5, 25, and 50 μM of EGCG suppressed tumor cell growth, invasion, and migration with measured reductions in the Bax/Bcl-2 ratio." (PMID 37568796, 2023). "The increased expression of Bcl-2, and more precisely the unfavorable ratio of the pro-apoptotic Bax protein to the anti-apoptotic Bcl-2 protein, determines the high resistance of this tumor to chemotherapy." (PMID 37195561, 2023). "miR-128 induces its tumor-suppressing effect, such as anti-proliferative and anti-metastasis effects, by inhibiting tumor-associated signaling pathways, such as WNT, ERK, EGFR, IGF1R, or BCL2." (PMID 37371047, 2023). "Moreover, Dreuw and co-authors demonstrated that fibroblasts, resulting from the differentiation of MSCs, mediated IL-6 secretion, leading to the overexpression of Bcl-2 and Bcl-xL in tumor cells and an inhibition of apoptosis following anti-cancer treatment." (PMID 37686315, 2023). "For SCLC with high BCL-2 expression, either in mice or in cell lines, venetoclax could robustly suppress tumor survival, which provides a basis for its clinical practice in SCLC patients harboring high BCL-2." (PMID 37894324, 2023). "We demonstrate that BCL2, an oncoprotein that is clinically targeted for the treatment of specific hematopoietic cancers, acts as a checkpoint to restrain the function of DCs with respect to tumor immunosurveillance." (PMID 37623817, 2023). "Tumor development is a multistep process that includes dysregulated energy metabolism, sustained proliferation, apoptosis evasion, and metastasis; GCR, SGK1, and Bcl-2 have been associated with these processes." (PMID 37370761, 2023). "For example, the simultaneous suppression of tumor cell survival by targeting factors such as Bcl-2 or TGF-ß using RNAi approaches while simultaneously increasing the immunogenicity of tumor cells by activating RIG-I with 5’-ppp RNAs can decrease tumor viability." (PMID 36798121, 2023).
tumor (continued). "The inhibiting of the pro-apoptotic proteins of the Bcl-2 community and blocking of the cytochrome C released from the mitochondria may increase chemoresistance in tumor cells." (PMID 37958539, 2023). "Interestingly, the mRNA level of the BCL-2 gene in the tumor sample injected with native CIMVs was increased by 1.4 (n = 5, **** p < 0.0001), while the mRNA level of the BAX gene remained unchanged, the BAX/BCL-2 ratio was 0.7." (PMID 36661524, 2023). "When the Bax/Bcl-2 ratio increases, excess Bax proteins form homodimers and activate apoptosis, but when the ratio decreases, Bax-Bcl-2 heterodimer formation elicits a survival signal for both normal and tumor cells." (PMID 37070074, 2023). "For example, TW-37, a small-molecule Bcl-2 inhibitor, induces S-phase arrest in tumours." (PMID 37834104, 2023). "The down-regulation of BCL2 mRNA expression in our study may suggest a potential role for BCL2 as a tumor suppressor or an indicator of poor prognosis." (PMID 38067251, 2023). "Interestingly, BCL-2 is overexpressed and located within the nuclei of several tumour-cell lines, and then colocalises and inhibits PARP1 to attenuate DNA repair." (PMID 37686461, 2023). "Therefore, our results indicate that the combined therapy of radiotherapy and siRNA-PD-L1 carried by attenuated Salmonella promotes tumor cell apoptosis by inhibiting Bcl-2, which facilitates cyto-c release." (PMID 37640735, 2023). "Unfortunately, resistance to venetoclax develops by several distinct mechanisms, including mutations in BCL2, epigenetic pathways, alterations in oxidative phosphorylation, alterations in BCL2 pathway, tumor microenvironment, genetic heterogeneity, and Ritcher’s transformation." (PMID 38263980, 2023). "Similarly, the upregulation of CCR7, XCR1, MHC-II molecules and CD86 on cDC1 was observed upon BCL2 inhibition with venetoclax in the MCA205 tumor model." (PMID 37623817, 2023). "Furthermore, Bcl-2 is clinically related to a poor tumour prognosis, and reduced expression of Bcl-2 sensitizes tumour cells to anti-cancer drugs and radiotherapy." (PMID 36734243, 2023). "Aconitine activates voltage-dependent Na+ channels in the thymus, promoting thymic T cell development, while also inhibiting Bcl-2 gene expression and activating the downstream gene Caspase-3 to promote tumor cell apoptosis through the regulation of the NF-κB signaling pathway." (PMID 37180714, 2023). "We found that exposure of tumor cells to EC significantly increases the Bax/Bcl2 ratio." (PMID 37687058, 2023). "In addition, we found that co-administration of p28 with iRGD and 5-FU down-regulated BCL2 in the tumor tissue homogenates." (PMID 37396945, 2023). "For immunohistochemistry, sections were obtained from paraffin-embedded tissue blocks and then applied for BCL2 immunostaining.Vitreous seeds cytologic analysis by H&E staining detected remarkable reduction of tumor cells in seeds treated by TPH-CMD-TCs-NPs as compared with other groups." (PMID 36937194, 2023). "Bcl2 and Bcl-extra-large (Bcl-xL) are antiapoptotic proteins highly expressed in tumor cells." (PMID 36674794, 2023). "NF‐κB in the NF‐κB/BCL2 signaling pathway silences apoptotic signaling to keep tumor cells alive." (PMID 37249289, 2023). "Nonetheless, whether synergistic effects between EBV and MYC/BCL2/BCL6 aberrations contribute to the pathogenesis of this subset of tumours remains to be established." (PMID 36836878, 2023). "Moreover, tumor cells treated with piperine showed increased Bax and decreased Bcl-2 expression, whereas the expression of p-PI3K, p-Akt, and p-mTOR uniformly decreased." (PMID 37762259, 2023).
tumor (continued). "Bak, Bcl-2, and Noxa were significantly differentially expressed by intra-tumor heterogeneity." (PMID 37958891, 2023). "It has also been demonstrated that MSCs expressing thrombospondin-1 (TSP-1) in a metastasis melanoma model decrease nodule apparition and exerted an anti-tumor effect via an activation of T cells, an upregulation of Bax pro-apoptotic protein, and a downregulation of Bcl-2 anti-apoptotic protein." (PMID 37686315, 2023). "Therefore, miR-625-5p can promote the expression of BCL2 and inhibit the apoptosis process of tumor cells to promote the occurrence and development of CRC." (PMID 36671913, 2023). "Tumor samples with an increased BCL2 mutation rate were enriched in tumor samples with BCL2 translocation (25/33, 76% vs. 8/33, 24% without BCL2 translocation; p < 0.01)." (PMID 37563306, 2023). "cb-EPS may induce tumor cell autophagy via regulation apoptotic factors since Bcl-2 expression decreased but Bak increased." (PMID 37514190, 2023). "A genome-wide CRISPR/Cas9 screen for gain-of-function phenotypes increasing DC-mediated cross-presentation that employed gene-edited iniDC revealed that B-cell lymphoma 2 (BCL2) acts as an endogenous checkpoint to suppress cDC1-mediated tumor immunosurveillance." (PMID 37907944, 2023). "Furthermore, MAP4K4 inhibition provoked tumor cell apoptosis (by increasing the Bax/Bcl-2 ratio) and inhibited tumor cell proliferation in a gastric cancer model." (PMID 37223681, 2023). "Thus, similar to our approach for limiting M.tb in a granuloma model, other labs have queried if specifically inhibiting MCL-1 and BCL-2 would limit tumor burden of cells that highly express both BCL-2 and MCL-1." (PMID 37864894, 2023). "Also, they indicated that nanomaterials with drugs enhanced cell death rate, and enhanced inhibition of tumor growth by affecting caspase, NF-κB, and Bcl-2 expression." (PMID 37289339, 2023). "The dysfunction of Bcl-2 is related to several types of diseases, including tumor development." (PMID 37237269, 2023). "Additionally, treatment with p28 with or without iRGD and 5-FU significantly enhanced the level of BAX while decreasing the level of BCL2 in the tumor tissue, which increases the ratio of apoptosis (P<0.01 and P<0.001, respectively)." (PMID 37396945, 2023). "In addition, integrative analysis of malignant PCNS DLBCL cells and extracerebral B-cell lymphomas supported the presence of a PCNS DLBCL-specific BCL2-high phenotype with a tumor-promoting feature." (PMID 37308475, 2023). "Therefore, we performed further experiments to explore the role of high-concentration PGD2 in drug response to venetoclax, which was the inhibitor of Bcl-2 and displayed greatly anti-tumor effects in hematological cancers." (PMID 36725845, 2023). "BCL2 inhibitor venetoclax could reduce BCL2‐BIM association and increase ROS resulting in tumor apoptosis." (PMID 37157237, 2023). "Importantly, overexpression of Bcl-2 in microvascular endothelial cells was sufficient to enhance angiogenesis and accelerate tumor growth." (PMID 37237269, 2023). "Impacting some signaling pathways like Wnt and β-catenin, and AKT/mTORC1 pathway, oncogenic factors (e.g., c-Myc) or apoptotic proteins, such as Bcl-2 can partly explain some mechanisms through which miR-184 may exert its role as a tumor suppressor." (PMID 38001121, 2023). "In this approach, a negative correlation was observed between miR-34a and its target BCL2 in HCT-15 cells based on the functional role of miR-34a as a potent tumor suppressor, as it selectively targets mRNAs involved in antiapoptotic mechanisms, exemplified by its regulation of BCL2 expression." (PMID 37761870, 2023). "Besides, Bcl-2 has been found to resist to cell death through promoting the recovery from DNA damage, suggesting the potential role of Bcl-2 inhibition in tumor treatment through DNA damage." (PMID 36725845, 2023).
tumor (continued). "The nano-complex reduced tumor volume and weight by more than threefold and twofold, respectively, as compared to control and free siRNA, indicating that siRNA was successfully delivered to the cancer location and that BCL2 was suppressed." (PMID 37111795, 2023). "In addition, WCP significantly suppressed p-STAT3Y705 and Bcl2 expression in tumor tissues (p < 0.05)." (PMID 37110586, 2023). "Moreover, the same study revealed C-PC abilities to generate ROS in the tumor cells, activate caspase-3 and downregulate the expression of antiapoptotic substance Bcl-2, thereby making cancer cells vulnerable to apoptotic death." (PMID 35567250, 2022). "Apoptosis of tumor cells can be accelerated by an increased level of an apoptosis promoter such as bax, while the decreased level of the apoptosis inhibitor bcl-2 increases, confirming the reduction of cells resistant to apoptosis in response to anti-cancer stimuli." (PMID 35682652, 2022). "For example, low expression of the lncRNA PANDAR predicted a poor prognosis of NSCLC and increased tumour cell proliferation by affecting the expression of the Bcl-2 protein family (Bax, Bad and Bcl-2) and caspase-3 via interaction with NF-YA at the transcriptional level." (PMID 35379783, 2022). "Moreover, the expression of Bcl-2 protein in tumor tissues was significantly downregulated in sh-BDNF-AS injected mice compared with that in sh-NC injected mice (p < 0.01)." (PMID 34980181, 2022). "BCL-2 inhibits apoptosis, and its overexpression and phosphorylation participate in the regulation of cell proliferation, playing an extremely important role in tumor formation and multidrug resistance." (PMID 36313628, 2022). "The NR4A1 mediator CsnB induced tumor cell apoptosis; this suppressive function of CsnB is associated with the translocation of NR4A1 from the nucleus to mitochondria to release the cytochrome C-depended Bcl-2 apoptotic pathway." (PMID 36052242, 2022). "The levels of Bcl-2 expression vary across cell types and tumor cell lines." (PMID 36013602, 2022). "Consequently, the activity of Bcl-2 inhibitors is inversely related to expression of Mcl-1 in tumor cells." (PMID 35574302, 2022). "Accordingly, DATS may inhibit tumour cell growth by increasing the expression of Bax in HepG2 cells whilst inhibiting the Bcl-2 expression, thereby inducing apoptosis and killing tumour cells." (PMID 37868628, 2022). "FMC7(±) and BCL2(±)weaker expression was weak in slightly over 20% of the tumor cells." (PMID 35167621, 2022). "Studies have shown that the Bcl-2 protein is highly expressed in many tumor cells, is the main antiapoptotic protein for sudden mitochondrial apoptosis, and plays an important role in the regulation of tumor cell apoptosis." (PMID 35445056, 2022). "BCL2 immunostaining has been reported to increase with tumor grades in MN, but the dysregulation of the control of apoptosis could impact in both directions, suggesting a potential role of BCL2 losses in cell-death control that would agree with our findings." (PMID 36011000, 2022). "The qRT-PCR detection of apoptosis-related genes (including Bax, BCL-2 and Caspase3) demonstrated that propofol increased the expression of pro-apoptotic Bax and Caspase3, but obviously decreased anti-apoptotic Bcl-2 levels in xenograft tumor tissues with DDP treatment." (PMID 35836137, 2022). "In non-small-cell lung cancer cell lines, lncRNA PVT1 can bind to miR-424-5p to decrease the expression of factors in tumor progression, such as CRAM, MMP-2, MMP-9 and Bcl2, to inhibit growth and increase the expression of Bax, thus suppressing the development of tumor cells." (PMID 35409396, 2022).